COL4A5 (collagen type IV alpha 5 chain)
Diseases named in the same sentence as COL4A5 in open-access papers (continued):
Sharing a sentence is not in itself a finding about the gene and the disease.
Alport syndrome (continued). "About 85% patients with Alport syndrome are due to mutations in the COL4A5 gene (X‐linked Alport syndrome, XLAS, MIM:301050), which encodes the α5 chain of type IV collagen." (PMID 28546999, 2017). "The exon originated from two separate introns as a result of an in‐frame COL4A5 deletion associated with a typical Alport syndrome." (PMID 28546999, 2017). "Deletions in the Xq22.3–Xq23 region, inclusive of COL4A5, have been associated with a contiguous gene deletion syndrome characterised by Alport syndrome with intellectual disability (Mental retardation), Midface hypoplasia and Elliptocytosis (AMME)." (PMID 27811305, 2017). "Twelve laboratories involved worldwide in mutation testing for Alport syndrome collaborated to submit 754 novel variants (504 COL4A5, 133 COL4A3, 117 COL4A4 variants) to the LOVD databases." (PMID 27627812, 2016). "There are occasional reports of individuals with two COL4A5 mutations, and others with autosomal recessive Alport syndrome and mutations in both COL4A3 and COL4A4 with a later age at onset of renal failure." (PMID 27627812, 2016). "X-linked Alport syndrome (XLAS), caused by mutations in the type IV collagen COL4A5 gene, accounts for approximately 80% of human Alport syndrome." (PMID 27959966, 2016). "In humans, type IV collagen gene mutations, e.g., COL4A5, lead to Alport syndrome, of which most symptoms, including renal dysfunction and auditory disturbance, are attributed to defects in the BM structure." (PMID 26451951, 2015). "In this study, we have analyzed COL4A5 mutations and disease characteristics in a Kazakh family with X-linked Alport syndrome." (PMID 26168235, 2015). "In humans, defects in the COL4A3/COL4A4/COL4A5 complex are the major cause of Alport syndrome, which is associated with a loss of BM integrity." (PMID 26451951, 2015). "For this, we examined four subjects from one Kazakh family clinically affected with X-linked Alport syndrome due to COL4A5 gene mutations." (PMID 26168235, 2015). "Approximately 80% of X-linked Alport syndrome cases result from mutations in the collagen α5 (IV) chain gene (COL4A5) on chromosome Xq24–48." (PMID 26168235, 2015). "Altogether, our data broadens the genotypic spectrum of COL4A5 mutations associated with mild Alport syndrome." (PMID 26168235, 2015). "Approximately 80% of Alport syndrome cases are caused by X-linked mutations in the COL4A5 gene encoding type IV collagen." (PMID 26168235, 2015). "It was discovered that overexpression of COL4A3 or COL4A4 in the embryonic lens results in microphthalmia and cataract, and mutation in COL4A3, COL4A3, and COL4A5 cause Alport syndrome." (PMID 25124159, 2014). "We suggest that the variant in COL4A5 is unlikely pathogenic because mutations in this gene have been previously associated with Alport syndrome [OMIM#301050]." (PMID 24721225, 2014). "Alport syndrome is associated with three genes: COL4A5 with the X-linked form (MIM 301050) while COL4A3 and COL4A4 are associated with the autosomal-recessive form (MIM 203780)." (PMID 23398688, 2013). "Given a clinical suspicion of Alport syndrome, genetic studies were performed, identifying a mutation in the COL4A5 gene." (PMID 22194875, 2011). "Background/Objectives: X-linked Alport syndrome (XLAS) arises from pathogenic variants in COL4A5." (PMID 42074603, 2026). "COL4A3, COL4A4, and COL4A5 are predominantly expressed in and critical for maintaining the structural integrity of the glomerular basement membrane, alterations in these genes lead to basement membrane disruption, which is the primary cause of Alport syndrome." (PMID 40351420, 2025). "Number of variants in COL4A3, COL4A4, and COL4A5 of Alport syndrome." (PMID 40949880, 2025). "Our findings highlight the importance of the molecular investigation of Alport syndrome, including the most common COL4A5:c.1871G>A and COL4A3:c.4421T>C variants, in the Polish population, with critical implications for genetic counselling and clinical practice." (PMID 40004525, 2025).
Alport syndrome (continued). "The COL4A5:c.1871G>A variant is predominant in Central and Eastern Europe and is the most frequent variant in the Polish population, accounting for 39% (44/113) of genetically confirmed X-linked Alport syndrome cases." (PMID 40004525, 2025). "An example is discovering pathogenic variants in the COL4A5 gene as a cause of Alport syndrome." (PMID 39945861, 2025). "Furthermore, a splice site mutation in the COL4A5 transcript appears to be less severe than mutations causing truncation in the X-linked Alport syndrome." (PMID 39201504, 2024). "COL4A5 is located on the X chromosome, and variants in COL4A5 cause X-linked Alport syndrome." (PMID 38745975, 2024). "Here, we report the cases of two related individuals (mother and son) who were diagnosed with COL4A5-related Alport syndrome due to a missense variant (p.Gly1170Ser) in a G-X-Y repeat and found to present the same highly unusual histopathological abnormalities on their kidney biopsies." (PMID 38668984, 2024). "Collagen IV genes including COLA4A3, COL4A4, and COL4A5, usually associated with hereditary forms of Alport syndrome, represent the emerging most frequent cause of FSGS in patients with otherwise unknown CKD or KF." (PMID 37728640, 2024). "Similarly, an exon-skipping strategy was evaluated in a mouse model of X-linked Alport syndrome, a rare kidney disease caused by mutations in COL4A5, and was shown to improve the collagen IV heterotrimer formation and prolong the survival of mice." (PMID 39201504, 2024). "Herein, we report a case of Alport syndrome caused by a de novo mutation in COL4A5." (PMID 37529776, 2023). "It is caused by mutations in COL4A5, leading to X-linked Alport syndrome (XLAS) for 85% of cases." (PMID 36981034, 2023). "X-linked Alport syndrome happens due to mutations in the COL4A5 gene." (PMID 38021591, 2023). "This study examined a Romani cohort for pathogenic variants in the COL4A3, COL4A4, and COL4A5 genes that are affected in Alport syndrome (AS), a common cause of genetic kidney disease, characterized by hematuria, proteinuria, end-stage kidney failure, hearing loss, and eye anomalies." (PMID 36844206, 2023). "However, further exome analysis revealed the maternally inherited p.(Gly624Asp) known pathogenic variant in COL4A5, causing X-linked Alport syndrome, which was also linked to aortic abnormalities in male patients." (PMID 37012328, 2023). "Hemizygous severe pathogenic variants in COL4A5 lead to classical Alport syndrome in boys and young men with hematuria, proteinuria, and rapid decline in estimated glomerular filtration rate as well as extrarenal manifestations of ocular and hearing abnormalities." (PMID 37180518, 2023). "X-linked Alport syndrome (XLAS) due to COL4A5 disease-causing variants is the most common form." (PMID 35360741, 2022). "Thus, two of the commonest hypomorphic variants are p.Gly624Asp in COL4A5 and p.Leu1474Pro in COL4A3. p.Gly624Asp in COL4A5 is found in about one in 3,000 of the European population or about one quarter of all Europeans with X-linked Alport syndrome." (PMID 35602506, 2022). "The COL4A5 hypomorphic variant, NM_000495.5:c.1871G>A substitution (rs104886142); p.(Gly624Asp) results in late-onset kidney failure and is the commonest pathogenic variant causing X-linked Alport syndrome in Central and Eastern Europe." (PMID 33854215, 2021). "Mutations in COL4A5 at Xq22 accounts for 80-85% of X-linked Alport syndrome patients." (PMID 33633790, 2021). "Alport Syndrome is a rare familial disorder of type IV collagen occurring in approximately 1 in 50,000 live births, and is most often caused by X-linked mutation in the COL4A5 gene." (PMID 34717572, 2021). "Mutations in COL4A3, COL4A4 and COL4A5 genes lead to Alport syndrome (AS)." (PMID 34508137, 2021). "In one of the infants, the gene that causes Alport syndrome was also identified (mutation COL4A5)." (PMID 34203932, 2021). "Alport syndrome is most commonly an X-linked disease, caused by COL4A5 mutation." (PMID 34717572, 2021).
Alport syndrome (continued). "Estimates of the prevalence of Alport syndrome vary from one in 5,000 to one in 53,000 of the population, but the frequent finding of likely pathogenic COL4A5 variants in normal reference datasets and cohorts with renal failure suggests that X-linked disease affects closer to closer to one in 5,000." (PMID 33854215, 2021). "Three modes of inheritance exist for AS: X-linked Alport syndrome (XLAS) (mutations involving COL4A5 on the X chromosome), autosomal recessive Alport syndrome (ARAS) (mutations in COL4A3 or COL4A4 on chromosome 2), and autosomal dominant Alport syndrome (ADAS) (mutations in COL4A3 or COL4A4)." (PMID 34858896, 2021). "While pathogenic COL4A5 variants cause x-linked Alport syndrome and bi-allelic mutations in COL4A3 or COL4A4 cause the autosomal recessive form, the interpretation of the biological significance of rare pathogenic but heterozygous COL4A3 or COL4A4 mutations can be challenging." (PMID 31049720, 2020). "X-linked Alport syndrome (XLAS) is an inherited renal disease caused by mutations in COL4A5 gene." (PMID 31576025, 2020). "Eighty-five percent of families have X-linked Alport syndrome (XLAS) with mutations in COL4A5 gene." (PMID 31576025, 2020). "Notably, patient 6 had both NPHS1 mutations (CNS) and COL4A5 gene mutations (Alport syndrome) along with active CMV infection." (PMID 31456999, 2019). "COL4A5 (NM: 000495.4) is the causative gene of X-linked Alport syndrome (XLAS)." (PMID 31481700, 2019). "In addition, the clinical phenotype and outcomes of individuals with Alport syndrome (especially females with COL4A5 mutation, heterozygous autosomal mutation) are heterogeneous." (PMID 29948307, 2018). "Alport syndrome is a hereditary kidney disease which manifests with hematuria, proteinuria, progressive renal failure, sensorineural deafness, or typical ocular changes, which are caused by mutations in the COL4A5, COL4A3, or COL4A4 genes." (PMID 29948307, 2018). "Therefore, identification of individuals with Alport syndrome, especially females with COL4A5 mutation and heterozygous autosomal mutation at high risk of rapid progression is indeed necessary for early and targeted treatment." (PMID 29948307, 2018). "Finally, in recent years other examples have been reported of patients with COL4A5 mutations and Alport syndrome, and phenotypes exacerbated by co-inheritance of mutations in other genes." (PMID 29764427, 2018). "Thus, the age at onset of renal failure in autosomal recessive Alport syndrome depended on mutation severity using the same criteria as for COL4A5 mutations." (PMID 27627812, 2016). "Alport syndrome results from mutations in the COL4A5 (X-linked) or COL4A3/COL4A4 (recessive) genes." (PMID 27627812, 2016). "However, mutations in COL4A5 (Alport’s syndrome) or auto-antibody recognizing α3(IV) (Goodpasture’s syndrome) result in progressive renal failure." (PMID 25992553, 2015). "Interestingly, X-linked Alport syndrome cases (male patients) with mild mutations in the COL4A5 gene, often present as phenocopies of TBMN, with a wide spectrum of phenotypes." (PMID 23516419, 2013). "Moreover, there is precedence for a Y position methionine to valine mutation in COL4A5 causing Alport syndrome." (PMID 21625620, 2011). "The diagnosis of Alport syndrome is suspected when an individual has the characteristic clinical features or a family history of Alport syndrome, and it is optimally confirmed by the demonstration of a disease-causing variant in the COL4A5, COL4A3, or COL4A4 genes." (PMID 37895203, 2023). "In conclusion, we identified a novel COL4A5 splicing variant causing X-linked Alport syndrome in a 3-year-old child, and we demonstrated the usefulness of genetic analysis and urinary screening in a 3-year-olds for the early diagnosis and treatment of Alport syndrome." (PMID 36045115, 2022).
Alport syndrome (continued). "Likewise, NPHS1 mutations are associated with nephrotic syndromes and the authors speculate that this mutation could modify the Alport Syndrome phenotype underlain by the COL4A5 mutation." (PMID 26179878, 2015). "A well-described hereditary GBM disease is Alport syndrome, which is associated with a progressive glomerular disease, hearing loss, and lens defects due to genetic variants in the genes COL4A3, COL4A4, or COL4A5." (PMID 41299396, 2025). "In the case of Alport syndrome, gene replacement therapy remains a challenge because the COL4A5 cDNA is too large to be accommodated within AAV vectors." (PMID 41417821, 2025). "Critically, the COL4A6 gene has been pointed out to be a candidate gene for Alport Syndrome by co-deletion in addition to the COL4A5 gene." (PMID 40718208, 2025). "Alport syndrome (AS) is a hereditary glomerulopathy caused by mutations in the COL4A3, COL4A4, or COL4A5 genes, leading to progressive kidney decline and extrarenal manifestations." (PMID 41243004, 2025). "In Alport syndrome, disruption of the GBM caused by variants in COL4A3, COL4A4, or COL4A5 causes podocyte dysfunction and proteinuria, proliferation of Bowman’s epithelial cells, and progressive glomerulosclerosis." (PMID 40527586, 2025). "Alport syndrome is a hereditary nephropathy caused by mutations in the COL4A3, COL4A4, or COL4A5 genes encoding type IV collagen, leading to structural defects of the glomerular basement membrane (GBM) and progressive kidney dysfunction." (PMID 41302105, 2025). "A recent publication identified 12 genes, including the three genes associated with Alport syndrome (COL4A3, COL4A4, COL4A5), on a 274‐gene panel with the potential for carrier manifestations during pregnancy." (PMID 40317772, 2025). "Alport syndrome is caused by variants in COL4A3, COL4A4, or COL4A5, which encode the α3α4α5 chains of type IV collagen." (PMID 41417821, 2025). "We aimed to determine the frequency of variants in the Alport syndrome genes (COL4A3, COL4A4 or COL4A5) in individuals under 18 years of age presenting with persistent microscopic haematuria to a single specialist centre in the UK over a 10-year period." (PMID 39349776, 2025). "X-linked Alport syndrome (XLAS), caused by mutations in the COL4A5 gene, is an X-linked hereditary disease typically characterized by renal failure, hearing loss, and ocular abnormalities." (PMID 40567900, 2025). "Alport syndrome (AS) is a hereditary kidney disorder caused by mutations in COL4A3, COL4A4, and COL4A5, which often lead to progressive renal failure." (PMID 41290692, 2025). "Alport syndrome is a rare genetic disorder resulting from the mutations in the genes COL4A3, COL4A4, and COL4A5 that affect the synthesis, assembly, deposition, or function of the glomerular basement membrane." (PMID 40212398, 2025). "This approach restores COL4A5 chain expression in glomerular and tubular basement membranes, reduces proteinuria, and extends survival in Alport syndrome mice." (PMID 40567900, 2025). "Alport syndrome is caused by pathogenic variants in COL4A3, COL4A4, and COL4A5 genes encoding the α3, α4, and α5 chains of collagen type IV, respectively." (PMID 40392259, 2025). "The condition follows four primary inheritance patterns, with X-linked Alport syndrome (XLAS) being the most common, accounting for approximately 80% of cases due to mutations in the COL4A5 gene." (PMID 40852417, 2025). "Alport syndrome involves chronic progressive kidney failure and extrarenal organ damage caused by COL4A3, COL4A4, and COL4A5 mutations." (PMID 39924725, 2025). "Genetically, Alport syndrome is caused by pathogenic variants in type IV collagen genes (COL4A3, COL4A4, and COL4A5), which lead to abnormalities in the glomerular basement membrane resulting in kidney dysfunction and progressive renal failure." (PMID 40852417, 2025).
Alport syndrome (continued). "X-linked Alport syndrome (XLAS) is the most common form, accounting for approximately 80% of cases, and is caused by pathogenic variants in the COL4A5 gene on the X chromosome." (PMID 40790091, 2025). "Alport syndrome is caused by loss-of-function variants in one of the genes encoding the type IV collagen α3α4α5 network—COL4A3, COL4A4, or COL4A5." (PMID 41417821, 2025). "Alport syndrome (AS) is a hereditary glomerular disease caused by mutations in the COL4A3, COL4A4, and COL4A5 genes." (PMID 40406358, 2025). "Alport syndrome (AS), a hereditary kidney disease with a high risk for renal failure, is attributed to pathogenic variants in genes COL4A3, COL4A4, and COL4A5 that encode type IV collagen." (PMID 39071776, 2024). "A mutation in the collagen type IV alpha-5 chain (COL4A5) gene is a genetic marker of CKD and is associated with Alport syndrome, a hereditary disease marked by kidney dysfunction and kidney fibrosis." (PMID 39728054, 2024). "Alport syndrome (AS) is a genetically heterogeneous disorder resulting from mutations in the collagen IV genes COL4A3, COL4A4, and COL4A5." (PMID 38433557, 2024). "In patients with an a priori clinical diagnosis of glomerulopathy, pathogenic variants in COL4A5 or COL4A3 were detected in eight individuals, confirming the diagnosis of Alport syndrome." (PMID 39363361, 2024). "Here, we report a unique form of COL4A5-related Alport syndrome that we have uncovered in two individuals from the same family." (PMID 38668984, 2024). "Alport Syndrome (AS) is the most common genetic glomerular disease, and it is caused by COL4A3, COL4A4, and COL4A5 pathogenic variants." (PMID 38790225, 2024). "Alport syndrome occurs at a prevalence of ~ 1% through mutations in COL4A3 (2q36.3), COL4A4 (2q36.3) or COL4A5 (Xq22.3)." (PMID 38668984, 2024). "Whole exome sequencing identified a novel heterozygous variant of COL4A5 NM_033380.3: c.2636 C > A (p.S879*) and a rare variant of GCK NM_001354800.1: c.1135 G > A (p.A379T) as the causes of Alport syndrome and monogenic diabetes, respectively." (PMID 36732323, 2023). "Alport syndrome is caused by basement membrane damage resulting from germinal mutations in the genes of type IV collagen (COL4A3, COL4A4, COL4A5 (collagen type IV alpha 3, 4, 5 chain genes))." (PMID 36982825, 2023). "A pathogenic variant in COL4A5 confirms the diagnosis of X-linked Alport syndrome, whereas variants in COL4A3 or COL4A4 confirm the diagnosis of Autosomal Dominant or Autosomal Recessive Alport Syndrome." (PMID 37895203, 2023). "X-Linked Alport Syndrome (XLAS) is an X-linked, dominant, hereditary nephropathy mainly caused by mutations in the COL4A5 gene, found on chromosome Xq22." (PMID 37635800, 2023). "Alport syndrome (AS) is the most common inherited glomerular disease caused by pathogenic variants of the COL4A3, COL4A4, or COL4A5 genes that encode type IV collagens." (PMID 36968823, 2023). "X-linked Alport syndrome (XLAS) is more severe than autosomal dominant form, which caused by pathogenic variants in the COL4A5 gene." (PMID 36968823, 2023). "In conclusion, we found a novel variant in COL4A5 and a rare variant in GCK in a family that presented with Alport syndrome and monogenic diabetes." (PMID 36732323, 2023). "In Alport syndrome, the substitution of glycine 852 and 325 by arginine is evident in the COL4A5 gene, which is responsible for basement membrane formation." (PMID 37189830, 2023). "In 2021, at the latest International Workshops on Alport Syndrome, the term AS spectrum disorder was accepted to refer to all disorders caused by variants in the COL4A3, COL4A4, or COL4A5 genes." (PMID 35880347, 2023). "Alport syndrome (AS) is a hereditary glomerulonephritis caused by COL4A3, COL4A4 or COL4A5 gene mutations and characterized by abnormalities of glomerular basement membranes (GBMs)." (PMID 37770589, 2023).